HPRT1 (hypoxanthine phosphoribosyltransferase 1)
Diseases named in the same sentence as HPRT1 in open-access papers (continued):
Sharing a sentence is not in itself a finding about the gene and the disease.
kernicterus (1 paper, 2023). A term used pathologically to describe BILIRUBIN staining of the BASAL GANGLIA; BRAIN STEM; and CEREBELLUM and clinically to describe a syndrome associated with HYPERBILIRUBINEMIA. "It is also notable that three other distinct aetiological groups apart from PANK2 exhibit awake resting FDG-PET cerebellar glucose hypometabolism, namely HPRT1, CP-Kernicterus and CP-Preterm." (PMID 36445406, 2023). "Temporal lobe glucose hypometabolism was found in KMT2B, HPRT1 and CP-Kernicterus." (PMID 36445406, 2023). "Brainstem hypometabolism occurred in 3/10 groups, namely HPRT1, CP-Kernicterus and CP-Preterm." (PMID 36445406, 2023). "HPRT1, PANK2, CP-Kernicterus and CP-Preterm all exhibited insula glucose hypometabolism." (PMID 36445406, 2023). "Cerebellar hypometabolism occurred in HPRT1, PANK2, CP-Kernicterus and CP-Preterm." (PMID 36445406, 2023). "Insula hypometabolism was observed in HPRT1, PANK2, CP-Kernicterus and CP-Preterm." (PMID 36445406, 2023).
Left ventricular diastolic dysfunction (1 paper, 2022). Abnormal function of the left ventricule during left ventricular relaxation and filling. "W. Nachar found that both GAPDH and HPRT1 were highly stable reference genes in a rabbit model of left ventricular diastolic dysfunction (LVDD)." (PMID 37170359, 2022).
leukemia (1 paper, 2013). A malignant (clonal) hematologic disorder, involving hematopoietic stem cells and characterized by the presence of primitive or atypical myeloid or lymphoid cells in the bone marrow and the blood. "qRT-PCR was performed for each of the 14 new genes, as well as for 5 standard control genes (GAPDH, ACTB, TBP, HPRT1, ABL1), on cDNA from a panel of 14 leukemia samples (10 AML, 4 ALL) plus one CD34+ cord blood sample (using equal amounts of RNA)." (PMID 24069164, 2013).
lymph node metastasis (1 paper, 2023). "Correlation analysis was performed to investigate the relationship between expression levels of PYGL and HPRT1, tumor size, and lymph node metastasis." (PMID 37371537, 2023).
multinodular goiter (1 paper, 2019). Nodular goiter characterized by more than one discrete tissue mass. "The expression characteristics of 12 candidate reference genes (GAPDH, ACTB, HPRT1, TBP, B2M, PPIA, 18SrRNA, HMBS, GUSB, PGK1, RPLP0, and PGM1) were assessed by qRT-PCR in 45 thyroid tissue samples (15 papillary thyroid carcinoma, 15 paired normal tissues and 15 multinodular goiters)." (PMID 31645594, 2019).
myocarditis (1 paper, 2022). Myocarditis is a condition that is characterized by inflammation of the heart muscle (myocardium). ", HPRT1 has been previously selected for normalization of gene expression profiles in cardiac tissue and blood cells in the study of myocarditis and PPIA was shown to be a functional internal control in study of healthy organ donors and cytokine expression in patients with LVAD." (PMID 35439923, 2022).
Neurodevelopmental delay (1 paper, 2020). "He presented with neurodevelopmental delay in the first year of life, and was diagnosed with LNS, with a substitution of phenylalanine to leucine in HPRT1 on the X-chromosome at 3 years of age." (PMID 32846834, 2020). "The patient presented with neurodevelopmental delay in the first year of life, and was diagnosed with LNS, with a substitution of phenylalanine to leucine in hypoxanthine-guanine phosphoribosyltransferase (HPRT) 1 gene on the X-chromosome at 3 years of age." (PMID 32846834, 2020).
non-small cell lung carcinoma (1 paper, 2022). A group of at least three distinct histological types of lung cancer, including non-small cell squamous cell carcinoma, adenocarcinoma, and large cell carcinoma. "Gedatolisib is a dual PI3K/mTOR inhibitor, and levels of mRNAs encoding HPRT1 (a key component of the purine rescue pathway) differ significantly between non-small cell lung cancer cells that are sensitive or resistant to gedatolisib." (PMID 35663326, 2022).
oral carcinoma (1 paper, 2022). "In our study, we found that mRNA levels of HPRT1 were significantly different in oral cancer tissues and corresponding adjacent tissues, and was much higher in cancer tissues." (PMID 35205603, 2022). "To verify the effect of HPRT1 on oral carcinoma cells, we used three specific sh-RNAs targeting HPRT1, and both could efficiently reduce the expression of HPRT1 in Cal27 and SCC25 cells by qRT-PCR and western blotting." (PMID 35205603, 2022). "Therefore, in the treatment of OSCC, blocking the HPRT1/MMP1/PI3K/AKT axis might be an important approach to reverse resistance to CDDP in oral cancer." (PMID 35205603, 2022). "Our study found that HPRT1 is highly expressed in many common cancers and corresponds to a poor clinical prognosis, and its malignancy and expression of resistance to CDDP in oral cancer has been identified, but there is very little research on HPRT1 in other tumor areas." (PMID 35205603, 2022).
ovarian tumour (1 paper, 2013). "Neither GADPH nor HPRT1 should be used as reference genes in studies on ovarian tumour tissue." (PMID 24001041, 2013).
postmenopausal osteoporosis (1 paper, 2024). Metabolic disorder associated with fractures of the femoral neck, vertebrae, and distal forearm. "We also predicted that HPRT1 is a potential target for metformin treatment of postmenopausal osteoporosis." (PMID 39500875, 2024).
prostate adenocarcinoma (1 paper, 2025). "It was determined that 21 proteins (DHX9, EIF5, HPRT1, INPP5B, MCM6, PPP6C, SYF2, etc.)whose expression was increased in PC3‐R cells based on label‐free nLC‐MS/MS analysis were consistent with both TCGA prostate adenocarcinoma N0 and N1 nodal metastasis status and correlation data." (PMID 39799471, 2025).
pulmonary TB (1 paper, 2025). "Our findings endorse a three-gene panel (PPIA, YWHAZ, HPRT1) for robust normalization of host gene-expression studies in both lesion tissue and PBMCs in pulmonary TB and highlight the necessity of context-specific reference-gene validation." (PMID 41303702, 2025). "To identify the most stable HKGs for analyzing material from patients with pulmonary TB, we selected eight genes—ACTB, B2M, GAPDH, HPRT1, PPIA, RPL13A, YWHAZ and UBC—that are most commonly employed as reference genes in clinical studies." (PMID 41303702, 2025).
rectal cancer (1 paper, 2023). A primary or metastatic malignant neoplasm that affects the rectum. "HPRT1, known for its involvement in purine and inosine synthesis, as well as its role in cell cycle regulation and DNA replication, exhibited increased expression in various malignancies, including breast, colon, and rectal cancers." (PMID 37760507, 2023).
rotator cuff tears (1 paper, 2015). "HPRT1+TBP+ACTB seems to be the best combination of reference genes for the analysis of involving different tendon samples of individuals with rotator cuff tears." (PMID 25768100, 2015). "In this study, we assessed the suitability of six reference genes frequently reported in the literature (18S, ACTB, B2M, GAPDH, HPRT1 and TBP) using tendon samples from individuals with and without rotator cuff tear by analyzing gene stability with four software packages." (PMID 25768100, 2015).
tumor (79 papers, 2003 to 2025). "Moreover, upregulated HPRT1 expression was detected in tumor specimens and was associated with evidently shortened survival time in patients with ESCC." (PMID 38485739, 2024). "It has been reported that HPRT1 is significantly elevated in multiple cancer types and is associated with a poor prognosis due to the increased demand for nucleotide synthesis during tumor cell proliferation." (PMID 35844514, 2022). "A significant role in CDDP chemoresistance and tumor progression has been attributed to the overexpression of HPRT1 in OSCC." (PMID 40740483, 2025). "In summary, our findings demonstrate that HPRT1 regulates carnosine metabolism under 3D conditions, influencing tumor growth." (PMID 41365579, 2025). "We performed metabolomic analysis of tumor tissues obtained from xenograft mouse models to investigate the metabolic alterations induced by HPRT1 KO in vivo." (PMID 41365579, 2025). "We further identified overlapping metabolites across the different culture models and the xenograft tumor model to compare the metabolic changes induced by HPRT1 KO (FDR < 0.05) in vitro and in vivo." (PMID 41365579, 2025). "To further elucidate the metabolic function of HPRT1 beyond its role in drug resistance, in this study, we explored its impact on tumor metabolism using 2D, 3D, and in vivo models." (PMID 41365579, 2025). "The study supports HPRT1 as a key driver of chemoresistance and tumor progression in OSCC, operating through MMP1‐mediated PI3K/AKT activation, and highlights its potential as a therapeutic vulnerability." (PMID 40740483, 2025). "In five tumors (COAD, HNSC, LUAD, THCA, and UCEC), we performed immunohistochemical analysis of HPRT1 in tumor and normal tissues." (PMID 38159260, 2024). "Immunohistochemical (IHC) staining of 64 paired tissue specimens from patients with ESCC suggested that the HPRT1 protein level was significantly elevated in tumor tissues compared with those in NAT (p < 0.001)." (PMID 38485739, 2024). "The positive expression is at the site of the active cell proliferation position, a possible link between HPRT1 and tumor tissue proliferation activity." (PMID 38159260, 2024). "This study evaluates the relationship between HPRT1 and clinical parameters, survival prognosis, and tumor immunity based on multiomics data from The Cancer Genome Atlas (TCGA) and the Gene Expression Omnibus (GEO) databases." (PMID 38159260, 2024). "In contrast, our study conducted a comprehensive pan-cancer analysis of HPRT1, unveiling previously unexplored insights into the expression, survival prognosis, and immune-related situations of tumor types." (PMID 38159260, 2024). "This denoted a higher tumor purity, indicating that a higher expression of HPRT1 corresponded to a greater content of tumor cells in these cases." (PMID 38159260, 2024). "The results showed that HIF-1α knockdown inhibited tumor growth, while HPRT1 overexpression restored it." (PMID 39343971, 2024). "Through cytological experiments, it was verified that HPRT1 plays a carcinogenic role in HNSC and is associated with tumor cell proliferation, migration, invasion, and apoptosis." (PMID 38159260, 2024). "Recent studies have found HPRT1’s upregulation in various cancers and its involvement in tumor development." (PMID 38159260, 2024). "The data acquired indicated that these xenografts with stably silenced HPRT1 showed delayed growth and had significantly reduced tumor volume and mass in comparison to the control mice (p < 0.05)." (PMID 38485739, 2024). "The HPRT1 content in tumor tissue from the READ dataset was higher than in corresponding paracancerous tissue." (PMID 38159260, 2024). "We analyzed the relationship between HPRT1 and the pan-cancer tumor microenvironment using the ESTIMATE algorithm." (PMID 38159260, 2024).
tumor (continued). "The integrated analyses revealed significant alterations in the purine salvage pathway, wherein the abundance of hypoxanthine/xanthine exhibited a positive correlation with HPRT1 expression and tumor size." (PMID 38485739, 2024). "Pearson correlation analysis revealed that the abundance of hypoxanthine and xanthine in tumor tissues was positively correlated with HPRT1 expression at both mRNA and protein levels (p < 0.05)." (PMID 38485739, 2024). "Meanwhile, up-regulated HIF-1α bound to the promoter of HPRT1 and transcriptionally activates HPRT1 expression, enhancing purine metabolism to maintain rapid tumor cell proliferation in EGFR-mutant LUAD." (PMID 39343971, 2024). "Next, we found that HPRT1 mRNA levels were markedly upregulated in tumor tissues compared to adjacent normal tissues." (PMID 35205603, 2022). "In this study, we first evaluated the expression and clinical value of HPRT1 mRNA and protein in tumor and healthy control tissues." (PMID 34231338, 2021). "Our results agree with this study because our analyses significantly improve the variation when we used the combination of ACTB and HPRT1, so this result supports their use in further gene expression studies in MM tumour samples for more reliable results." (PMID 34940125, 2021). "The sex‐based analysis for both cohorts indicated the significant overexpression of HPRT1 gene level in tumor samples of both sexes compared with the normal tissues." (PMID 34231338, 2021). "The findings showed negative HPRT1 staining in normal oral mucosa of one patient, and moderate and strong HPRT1 staining in tumor tissues of one and three patients with HNSCC, respectively." (PMID 34231338, 2021). "The relative mRNA ratio of human HPRT1 to mouse GAPDH47 indicated that ZFP36 strikingly decreased the proportion of colonized tumor cells in LNs." (PMID 34853315, 2021). "To evaluate in vivo effect of LSD2 on tumor metastasis, we quantified mRNA expression of human housekeeping gene HPRT1 in mouse lung tissue samples by real-time RT-PCR using a probe that does not cross-react with its mouse counterpart." (PMID 29137219, 2017). "In contrast to the protein expression data, there was a notable increase in transcript expression relative to HPRT-1 in tumor cells compared to cultured cells for all transcripts except 22Rv1 CK2α′." (PMID 27557516, 2016). "While Gusb and Hprt1 were expressed at consistent levels, Gapdh and Actb showed the least consistency between tumours." (PMID 25495686, 2015). "Since Hprt1 expression showed the least variation among tumours and among tumours, spleen and TDLN, this gene was selected for data normalization." (PMID 25495686, 2015). "In order to evaluate and screen the optimal endogenous control for lncRNAs analysis of tissues and cells, the candidate reference genes (GAPDH, TBP, β-actin and HPRT1) were measured in 21-pair ESCC tumor tissues and adjacent normal tissues." (PMID 25608466, 2015). "Expression of AD1 and AD2 was related to hypoxanthine phosphoribosyltransferase 1 as a housekeeping gene in breast tissue using quantitative RT-PCR, and the results were related to clinicopathological features of the tumours." (PMID 20678196, 2010). "This RT-qPCR study showed that there are statistically significant (p < 0.05) differences in the expression levels of HPRT1 and 18S rRNA in 'normal-' versus 'tumor stomach tissues'." (PMID 20507635, 2010). "The ANOVA analysis (p < 0.05) confirmed that there was a significant increase in both GAPDH and HPRT1 expression levels in tumor samples compared to normal tissues." (PMID 19014639, 2008). "Moreover, HPRT1 KO had a minimal effect on cell proliferation under in vitro 2D culture conditions but significantly suppressed tumor formation in mouse xenograft models." (PMID 41365579, 2025).
tumor (continued). "Downregulation of HPRT1 reduced resistance, increased apoptotic responses, and impaired tumor growth, indicating that targeting this axis may enhance therapeutic efficacy and serve as a prognostic and therapeutic avenue in OSCC management." (PMID 40740483, 2025). "In addition, differences in metabolic profiles between the 2D and 3D culture models following HPRT1 KO demonstrate the impact of the extracellular environment on tumor metabolism." (PMID 41365579, 2025). "The expression of HPRT1 was different in various tumor tissues." (PMID 38159260, 2024). "The question of how HPRT1 interacts with identified sensitive drugs influencing tumor progression remains unclear." (PMID 38159260, 2024). "The significance of HPRT1 in tumor immunotherapy has also been investigated." (PMID 38159260, 2024). "In addition, tissue sequencing data suggested that HPRT1 mRNA expression was significantly enhanced in tumor tissues in comparison to that in NAT (p < 0.001)." (PMID 38485739, 2024). "Contrarily, in GBM, lower levels of tumor cells were found in the high HPRT1 expression group." (PMID 38159260, 2024). "Finally, inhibition of HPRT1 coupled with EGFR-TKIs significantly inhibits the tumor growth of EGFR-mutant LUAD." (PMID 39343971, 2024). "In the tumor microenvironment, HPRT1 was predominantly expressed in tumor cells." (PMID 38159260, 2024). "Elevated HPRT1 levels in tumors may contribute to immune evasion, fostering, and immunosuppressive tumor microenvironment." (PMID 38159260, 2024). "Moreover, the contents of purine nucleotides were decreased in PC9-shHIF-1α cells-derived tumor tissues compared to control group, while the overexpression of HPRT1 restored the contents of purine nucleotides." (PMID 39343971, 2024). "The results indicated that knockdown of HPRT1 suppressed tumor growth and decreased tumor weight." (PMID 39343971, 2024). "The expression of HIF-1α, HPRT1 and Ki67 in mouse tumor tissues was detected by IHC." (PMID 39343971, 2024). "The overexpression of hypoxanthine phosphoribosyltransferase 1 (HPRT1) can contribute to the formation of an immunosuppressive tumor microenvironment by significantly reducing the activation of immune cells (B cells, CD8 + T cells, CD4 + T cells, macrophages, and neutrophils)." (PMID 34422810, 2021). "However, consistent with flow cytometric analysis of marrow isolated from SUM159-inoculated mice, we detected tumor cells by qPCR analysis for human B2M expression in 2/8 (25%) mice and human HPRT1 in 3/8 (38%) mice." (PMID 30250146, 2018). "In contrast, HPRT1 was identified as the least stable reference gene by all algorithms, but it was reported as the single best reference gene in 80 normal and tumor samples." (PMID 25617865, 2015). "As the stable expression of HPRT1 and PPIA between normal and tumor endometrial samples fulfill the basic requirement of a reference gene to be used for normalization purposes, HPRT1 expression showed significant differences between samples from low-grade and high-grade tumors." (PMID 25473950, 2014). "In case of normalization by RPL29 which was predicted as most stable single reference gene in NormFinder and most stable combination with HPRT1 in geNorm, the high-low pattern of RQ difference between normal and tumor was similar to RQ by HPRT1 though there were difference in three patients." (PMID 20507635, 2010). "Besides, the observed up‐regulation of the HPRT1 expression in tumor tissues may be a valuable biomarker for diagnosis, prognosis and targeted treatment of patients with HNSCC." (PMID 34231338, 2021). "We then performed qRT-PCR for RD3 expression in the GBM tissues from the Evangelisches Krankenhaus cohort and found a significant downregulation of RD3 expression in GBM compared to non-tumor tissue (expression normalized to TBP and HPRT1)." (PMID 40234400, 2025). "Using publicly available patient tumor data, we found that H3K27M tumors had an inverse correlation between patient outcome and HPRT1 expression." (PMID 38594734, 2024).